IL2 (interleukin 2)
Diseases named in the same sentence as IL2 in open-access papers (continued):
Sharing a sentence is not in itself a finding about the gene and the disease.
tumor (continued). "We also demonstrate that pemetrexed can synergize with PD-1/PD-L1 blockade to enhance the production of IL-2, TNF-α and IFN-γ within the tumor microenvironment in the mouse syngeneic models." (PMID 33243934, 2020). "Th1 cells mainly secret cytokines such as IL-2, IL-12, TNF-α, and IFN-γ, which can enhance the cytotoxicity of immune cells to kill tumor cells and make the body's anticancer immune response stronger." (PMID 32351590, 2020). "It was noted that by day 9 and before the second dose of NKTR-214 or IL-2, a substantial decrease in the BLI signal was observed in spleen and tumor, independently of the treatment, consistent with a q9d dosing schedule." (PMID 32005809, 2020). "Experimental mice models have shown that NKG2D/ligand interactions on NK cells can induce a strong secretion of IL-2 and IFN-γ,which contribute to suppressing tumor growth by modulating tumor microenvironment." (PMID 33076479, 2020). "CD4+ transfer into lymphodepleted animals or regulatory T (Treg) cell depletion promoted GzmB expression by tumor-infiltrating CD4+, and this was prevented by interleukin-2 (IL-2) neutralization." (PMID 31924474, 2020). "Our findings underscore the role of Treg cells, IL-2, and Blimp-1 in controlling the differentiation of cytotoxic CD4+ T cells and offer a pathway to enhancement of anti-tumor activity through their manipulation." (PMID 31924474, 2020). "Taken together, our findings have established that ex vivo HSP70/IL-2 stimulation potently activates NK cells, which enables them to effectively cross the BBB and target tumor cells in our in vivo rat model of induced GBM." (PMID 32218162, 2020). "Additional studies have verified that DEX activates CD8+ and CD4+ T cells and induces an anti-tumor immune response by exosomal CD80 and endogenous IL-2 in vivo." (PMID 33183286, 2020). "CD4+ T cell transfer into lymphodepleted animals or Tregs depletion promoted GzmB expression by tumour-infiltrating CD4+, an effect prevented by IL-2 neutralization." (PMID 32680511, 2020). "As expected, upon stimulation with PD-L1 on tumor cells, PD-L1 CAR-Jurkat T cells produced high levels of IL-2, which indicated the binding of this anti-PD-L1 scFv to PD-L1 is capable of transducing signal into T cells and thereby applicable in designing CCR." (PMID 33292688, 2020). "Further, consistent with the findings obtained in vitro, the combined treatment of the aptamer and antibody significantly increased the levels of both IL-2 and IFN-γ compared with each single treatment, as assessed by RT-qPCR on tumor samples." (PMID 32892748, 2020). "Mice treated with G100 also had significantly higher levels of tumor antigen-specific CD4 and CD8 T cells that secrete IFNγ and IL2 after in vitro stimulation with A20 cells." (PMID 32974162, 2020). "It has been shown that an increase in cytokines, such as IL-2 and IFN-γ, can activate NK cells, whose activity is reduced during EAT growth, and thus contribute to the natural resistance of tumor growth." (PMID 33261130, 2020). "It was also shown that specific antibodies against cytokines TNFα, IFNγ and IL-2, which were co-incubated with Tag7-PBMC, decrease the cytotoxic effect of Tag7-PBMC against tumor cells." (PMID 33291689, 2020). "Pathology of the CCR4 IT‐alone group showed sporadic tumor cell areas, demonstrating that CCR4 IT treatment is more effective against the tumor cells than IL2 fusion toxin treatment." (PMID 32107846, 2020). "In monitoring the percentages of T cell subpopulations, the proliferation of lymphocytes in draining lymph nodes from tumor-bearing Siah2−/− or WT mice was assessed prior to and following stimulation in culture with CD3/CD28 antibodies combined with IL2." (PMID 31911617, 2020). "CD8+ T cells and CD3+ T cells liberate anti-tumor molecules such as interferon-γ (IFN-γ) and IL-2, and cytotoxic molecules perforin and granzyme B are also secreted by effector CD8+ T cells, making them effective to kill tumor cells." (PMID 33182298, 2020).
tumor (continued). "Increased expression of genes associated with Cγ chain cytokine signaling and the response to IL-2 in Trp1 Th-ctx is consistent with the cytokine milieu induced by lymphodepletion and could offer mechanistic insights into the acquisition of cytotoxic activity by tumor-reactive CD4+ T cells in vivo." (PMID 31924474, 2020). "Recently, PEGylated interleukin-2 (Bempegaldesleukin) has been shown to provide superior anti-tumor activity over native IL-2 and systemically expands anti-tumor CD8+ T cells while inducing Treg depletion in tumor tissue." (PMID 32917054, 2020). "In the presence of the target tumor cells, CAR-T cells together with anti-PD1 antibody can secret more IL-2 and IFN-γ and eliminate tumor cells more efficiently in comparison with CAR-T cells alone." (PMID 32766150, 2020). "This led to markedly reduced IL-2 production and compromised immune control of the B cell transforming EBV latency III infection, resulting in elevated viral loads and tumor formation akin to PTLD." (PMID 32251475, 2020). "Compared to the control group, the content of anti-tumor immunity-related cytokines IFN-γ, TNF-a, IL-2, and IL-5 increased, while IL-6, related to inhibiting anti-tumor immunity, decreased in the TME." (PMID 32802195, 2020). "In the present study, we systematically analyzed the impact of IL-2, IL-12, and IL-18 in parallel with TCR stimulation on proliferation, cytokine production, and anti-tumor activity of γδ T cells." (PMID 31947966, 2020). "At last, our results also indicated oncolytic bacteria P. aeruginosa produced durable tumor regression and reshaped the systemic and tumor-infiltrating immune cells profile changes, especially IFN-γ- and IL-2-producing lymphocytes." (PMID 33643911, 2020). "Consistent with results of in vitro cytotoxicity assays, both dPD1z T and CARPD-L1z T cells inhibited the growth of H460GL cells in immunodeficient NSI (NOD/SCID/IL-2 g−/−) mice, and CARPD-L1z T cells showed superior anti-tumor effects." (PMID 32514352, 2020). "One interesting approach can be the co-activation of macrophages (MΦs) (retinoic acid), NK cells (IL-15, IL-22, and IL-23), cytotoxic T cells (CTLs) (IL-2, TNF-α, IFN-γ), and the acquisition and presentation of tumor antigens by dendritic cells." (PMID 33276556, 2020). "Treatment with CEA-TCB triggered secretion of pro-inflammatory cytokines (IFNγ, TNFα, IL-2) and several chemotactic molecules (CXCL9, CXCL10, CXCL11, CXCL13) indicating the generation of a highly inflamed tumor microenvironment." (PMID 33330050, 2020). "In a similar study, APS upregulated the expression of TNF-α, IL12, and IL2, whereas it decreased the levels of IL10 and downregulated the expression of multidrug resistance 1 mRNA and P-glycoprotein in H22 tumor-bearing mice." (PMID 32265719, 2020). "The reduced expression of anti-tumour cytokines in CXCL9-treated mice was further proven by the observation that serum level of TNFα, IL2, and IFNγ in CXCL9-treated mice was remarkably suppressed." (PMID 31913856, 2020). "Ciji-Hua'ai-Baosheng granules also upregulated the expression of IL-2, IFN-γ, and TNF-α in both serum and tumor tissues in vivo, which can help resist immune-related injuries caused by chemotherapy." (PMID 32595757, 2020). "Self-assembled NPs increase the production of inflammatory cytokines such as IL-2 and IFN-γ in activated leukocytes, generating powerful immune responses to low immunogenic tumours." (PMID 32610601, 2020). "To assess cytotoxic activity of cytokine-treated NK cells, we co-cultured IL-2/IL-15-treated NK cells (E) and green fluorescent protein (GFP)-labeled GBM tumor cells (T) at different ratios." (PMID 32218162, 2020). "ID-8 induced the death of tumor cells more efficiently than Ipilimumab, by significantly increasing the secretion of IL-2 and IFNγ cytokines by NK cells, and leading to increased cell lysis with a higher lactate dehydrogenase (LDH) release by tumor cells." (PMID 32781690, 2020).
tumor (continued). "In both spleen and tumor, ACT + NKTR-214 increased polyfunctionality by 1.7 and 10 fold, respectively, compared to ACT + IL-2." (PMID 32005809, 2020). "Here, we demonstrated that the combined rV-neuT+CUR treatment was more effective at reducing tumor growth and increasing mouse survival, anti-Neu humoral response, and IFN-γ/IL-2 T-cell release in vitro than the individual treatment." (PMID 32423101, 2020). "We evaluated the plasma concentrations of Th1 (IL-2, IFN-γ, and TNF-α), Th2 (IL-4, IL-5, IL-6, and IL-10), Th9 (IL-9), and Th17 (IL-17A, IL-17F, IL-21, and IL-22) cytokines in tumor-bearing mice by flow cytometry." (PMID 32802733, 2020). "IL-1β, while promoting increased synthesis of IL-2, IL-6, and TNF-α, also acts as a tumor growth promoting molecule in conditions of chronic inflammation." (PMID 33718121, 2020). "In particular, they found that combination therapy with GQD and anti-PD-1 induced the frequency of CD8+ T cells in tumor tissues as well as peripheral blood, and increased IFN-γ and IL-2, but decreased PD-1." (PMID 32733246, 2020). "In an early preclinical study, bone marrow-derived dendritic cells (BMDCs) expressing IL-12 were more effective than DCs expressing IL-2 in controlling the growth of B16F10 melanomas and generating tumor-specific CTL activity." (PMID 33178203, 2020). "Both cytokines have been shown in animal and human models to have anti-cancer properties: IL-2 enhances the growth and activation of natural killer cells and CD-8+ T-cells, while IFN-α enhances tumor antigen presentation, among other characteristics." (PMID 32429554, 2020). "However, it is conceivable that in older adults who might exhibit lower basal levels of IL-2 or IFN-alfa, or might have an impaired capacity to produce these cytokines, these individuals might exhibit a greater risk of cancer and poorer anti-tumor responses." (PMID 33597950, 2020). "Th1 enhances and expands the cellular immune response process by secreting interleukin (IL)-2, IFN-γ and other cytokines and induces other immune cells to exert anti-tumor effects." (PMID 32626535, 2020). "Secondly, in the presence of interleukin (IL)‐2, IL‐5 and other cytokines, combination therapies enhance CD8 T‐cell activation and their ability to attack tumour cells." (PMID 33078904, 2020). "Next, we assessed the ability of lamina propria T cells from unaffected tissue and tumor tissue to produce some of the cytokines important in tumor immunity (IFN-γ, IL-2, IL-17A, and TNF)." (PMID 32185408, 2020). "Th1 cells secrete interferon-γ (IFN-γ), Interleukin-2 (IL-2), and tumor necrosis factor (TNF-α) that result in an anti-cancer tumor immune microenvironment." (PMID 32370060, 2020). "In the present study, we characterized IL-2 and HLA class I expression, and T, CD8+ T cells and NK/monocytes in human PTC, PTC+HT and their adjacent non-tumor tissues." (PMID 32368308, 2020). "A statistically significant upregulation of IL-2 and IFN-γ was seen in serum collected from the peripheral blood of tumor-bearing mice treated with 1400W and RT." (PMID 32226302, 2020). "18F-labeled IL-2 was developed as a PET tracer and its uptake was shown to increase upon tumor treatment." (PMID 33584676, 2020). "Genes whose growth profiles most similarly match the T cell growth when stimulated by IL-2 include genes such as: TMEM74B and TTC36, a transmembrane protein and a tumor suppressor." (PMID 33105566, 2020). "We determined that OAd.TNFa-IL2 induced DAMP and PAMP release and consequent tumor microenvironment modulation." (PMID 32225009, 2020). "The peak of T cell infiltration in the tumor after the second NKTR-214 dose was reached at day 14, with an average radiance 6-fold higher in the ACT + NKTR-214 group compared to the ACT + IL-2 group." (PMID 32005809, 2020). "In order to evaluate the organization and interaction of stem and tumor cells, native hADSCs, hADSCs-BFP or hADSCs-IL2 and SH-SY5Y cells were co-cultured on the Matrigel matrix for 120 h." (PMID 32560387, 2020).
tumor (continued). "Recent studies have also identified Fractalkine–CX3CR1 interactions in HCC cell cycle and CX3CL1 dependent cytotoxic T cell, IL-2, and IFN-γ responses that block tumor development." (PMID 33718121, 2020). "In this study, immunohistochemical expression of TNF-α, IL-6, IL-1β, and IL-2 in GEP-NENs was evaluated and correlated with the proliferation, tumor grade, tumor, node, metastasis (TNM), and outcomes." (PMID 32156252, 2020). "Their data revealed that overexpression of this chimeric receptor in anti-MUC1CAR T cells not only results in phosphorylation of STAT3/STAT5/ERK and proliferation, in a similar way to IL-2, but also can kill MUC1-positive tumor cells." (PMID 32391013, 2020). "The immunoconjugate 10_12-CL4 induced the death of tumor cells more efficiently than both the parental moieties, significantly increasing the secretion of IL-2 and IFNγ cytokines by lymphocytes, as well as LDH release by tumor cells." (PMID 31470510, 2019). "Based on this tumor cell to T cell ratio, we evaluated the enhancing effect of FITC-YT-16 incubation on T cell activity by measuring IL-2 and IFN-γ levels in the culture supernatant." (PMID 30699956, 2019). "IL-2, IFN-gamma and TNF-alpha secretions were significantly reduced by continuous exercise in the tumor-bearing mice fed a high-fat diet." (PMID 31528182, 2019). "For instance, IL2 was shown to be necessary for NK1.1 induced proliferation and IL2-activated NK cells stimulated through NK1.1 had increased cytotoxicity toward tumour target cells." (PMID 31595191, 2019). "Decreased expression of IL-2 in both CD8+ and CD4+ subsets was connected with the late stage of the neoplasm." (PMID 31582940, 2019). "Tumor apoptosis, CD8+ cell infiltration and increased interferon-gamma (IFNγ) and interleukin-2 (IL-2) levels were only seen in PSMA-positive PC3 tumors." (PMID 31619289, 2019). "HPK1 KO T cells were demonstrated to be resistant to PGE2-mediated suppression of T-cell proliferation, IL-2 production, and apoptosis, suggesting that PGE2 utilizes HPK1, at least in part, to suppress T cell-mediated anti-tumor responses." (PMID 30913212, 2019). "The fraction of CD8+ T cells (IL-2+, TNFα+ or IFN-γ+) decreased in CD8+ T cells from 4T1-bearing mouse spleens compared with CD8+ T cells from spleens of tumour-naive mice." (PMID 31594465, 2019). "In addition, it has been shown that an increased absolute platelet counts might reflect degree of the systemic inflammation induced by tumor, because pro-inflammatory mediators such as interleukin-2, interleukin-3, and interleukin-6 can stimulate the proliferation of platelet progenitor cells." (PMID 31921649, 2019). "An IL-2 mutein with decreased affinity to CD25 (mainly expressed on pulmonary endothelial cells and Treg cells) was developed to possess more effective tumor therapeutic effects than the wild-type IL-213,14." (PMID 31462678, 2019). "Furthermore, exosomes derived from MDSCs have been reported to promote tumor progression by facilitating the polarization of M1 macrophages with a tumoricidal phenotype, to a tumor-promoting M2 macrophage, via inhibition of macrophage production of IL-2 production." (PMID 31555295, 2019). "Upon administration, we suspect that these IL-21/IL-2-expanded TILs or TRUCKs would be best maintained by engineering them to secrete IL-7 and IL-15, which we hypothesize will further promote their persistence and memory recall responses to prevent tumor relapse in patients." (PMID 30842774, 2019). "Combining the nanobody-mediated delivery of IL-2 and IFN-γ with tumor-specific antibody therapy resulted in tumor growth inhibition, which coincided with increased CD8+ T cell numbers." (PMID 31695800, 2019). "Co-delivery of IL-2 and PCT resulted in a 2.5-fold lower tumor volume after 17 days of treatment than with individual drug loaded nanoparticles." (PMID 30875934, 2019).
tumor (continued). "Given that cytokines play critical roles in the proper establishment of anti-tumor immunity, we examined the levels of IFN-γ, IL-6 and IL-2 in both murine- and human-derived CD8+ T cells and in tumor cell coculture systems." (PMID 31511064, 2019). "Pre-incubating NK cells with IL-2 results in the generation of a lymphokine-activated killer (LAK) cell, whereas pre-incubating with target tumor cells generates a “tumor-primed” NK cell (TpNK)." (PMID 31242243, 2019). "Meanwhile, the downregulation of PDL1 expression increased IFN‐γ, IL‐2, and TNF‐α expressions in mouse serum and tumor tissue samples and decreased IL‐10 expression." (PMID 31557409, 2019). "IL-2, TNF-α, and IFN-γ immune factors enhanced the function of tumor-killing cells such as CD3+CD4+T and NK cells." (PMID 31256187, 2019). "We also compared the expression levels of perforin, granzyme B, IFN-g, TNF-a, and IL-2 of CD8+ T cells between PBMCs and tumor in each T cell subset." (PMID 30682105, 2019). "Rnf5−/− tumor-infiltrating CD4+ and CD8+ lymphocytes (TILs) also displayed greater effector function, including enhanced IFN-γ, TNF-α, and IL-2 production." (PMID 30940817, 2019). "As was observed for NK cells co-cultured with B16 tumour cells, NK1.1 stimulated NK cells increased the expression of CD25, suggesting that these cells would be more responsive to IL2 cytokine." (PMID 31595191, 2019). "Lastly, many T cell stimulatory cytokines including IL-2, IL-7, and IL-15 play an important role in enhancing anti-tumor immunity, but whether or not these cytokines render T cells resistant to the suppressive effects of Treg cells in the context of anti-tumor immunity is unclear." (PMID 31058083, 2019). "In 1989, autologous LAK cells with IL-2 were given to 10 HCC patients, tumor regression was observed in two patients, and the rest maintained stable disease (SD)." (PMID 31614472, 2019). "IL-2 promotes the activation and proliferation of T lymphocytes and produces cytokines such as IFN-C and TNF-β, which can indirectly kill tumor cells and induce the production of T lymphocytes and NK." (PMID 31781277, 2019). "Both IL-2-nanobody and IFN-γ-nanobody synergized with an anti-TAA antibody for tumor growth inhibition." (PMID 31544819, 2019). "In the last few years, however, IL-2 consumption by CD25-positive regulatory T cells (Tregs) and subsequent inhibition of tumor-specific T cells has garnered increasing attention." (PMID 31195686, 2019). "After treatment with COS, significantly elevated concentrations of Bax and reduced expression of Bcl-2 in tumor tissues, as well as elevated levels of TNF-α, IL-2, Fas and Fas-L in mice serum were observed (p < 0.05)." (PMID 30791594, 2019). "Herein we show that murine NK cell interaction with tumour cells induces the expression of CD25, the high affinity IL2 receptor, rendering these NK cells highly sensitive to the T cell-derived cytokine IL2." (PMID 31595191, 2019). "In consistence with regressed tumor growth, NIH3T3-CM-educated OT-1 cells prolonged mice survival than medium alone-cultured OT-1 cells with concomitant IL-2 therapy (right)." (PMID 31031760, 2019). "In particular, interferon response and IL2/STAT5 signaling pathways as well as innate and adaptive immune responses were missed when comparing tumor with the gNAT specimens." (PMID 31454993, 2019). "The expression of Th1 cytokines (IL-2, TNF, IFN-γ) and Th2 cytokines (IL-4, IL-5, IL-6, IL-10) were examined in frozen tumor tissues from 80 GC patients by ELISA." (PMID 31417548, 2019). "The immunostimulatory liposomes had remarkable tumor accumulation and improved anti-CD137 mAb and IL2 localization compared with their soluble forms." (PMID 31695803, 2019). "DCs loaded with the lysate of tumor cells infected with NDV (viral oncolysate, VOL) trigger potent anti-tumor immunity by promoting the secretion of IFN-γ and IL-2 from T cells." (PMID 31480379, 2019).